MTOR (mechanistic target of rapamycin kinase)
Diseases named in the same sentence as MTOR in open-access papers (continued):
Sharing a sentence is not in itself a finding about the gene and the disease.
cancer (continued). "Furthermore, it decreased the expression of glycolysis enzymes, showing PD-L1’s role in glucose consumption through the ATK/mTOR pathway in cancer cells." (PMID 37193972, 2023). "Constitutive activation of PI3K/AKT/mTOR has been reported in cancer." (PMID 36768977, 2023). "The PI3K/Akt/mTOR (PI3K: phosphoinositide 3-kinase, Akt: serine/threonine kinase 1, and mTOR: mammalian target of rapamycin) signaling pathway has attracted high attention for cancer treatment owing to its role in the differentiation, proliferation, invasion, and migration of cancer cells." (PMID 37630248, 2023). "The PI3K/Akt and mTOR signaling pathways are two pathways crucial to many aspects of cell growth and survival in physiological as well as in pathological conditions (e.g., cancer)." (PMID 37298208, 2023). "We hypothesized that a combination of mefloquine and mTOR inhibition will affect ML viability and synergize to cancer cell death." (PMID 36816923, 2023). "Interestingly, the mTOR signaling pathway also regulates apoptosis, programed cell death involved in various physiological and pathophysiological processes including cancer." (PMID 37180606, 2023). "Progress in targeting mTOR signaling could significantly improve anti-cancer treatments and benefit patients in clinical settings." (PMID 38275385, 2023). "The discovery of new members of oncogenic pathways, such as that of TTK and potentially PRKACA in the PI3K/AKT/mTOR pathway in this study, may help the identification of alternative targets for cancer treatment." (PMID 37352361, 2023). "GOLPH3 exerts its effect by modulating key signaling pathways such as the PI3K/Akt/mTOR pathway which plays a vital role in cell survival, proliferation and migration—providing targetable precision medicine strategies against gastroenterological cancers." (PMID 37508488, 2023). "Therefore, in this study, we also looked for changes in insulin/IGF-1, mTOR, NF-B, and Sirtuin signaling pathways, as well as signaling pathways related to cancer, in relation to the increase in the level of CR." (PMID 36757838, 2023). "Lastly, arginine, glutamine and the BCAAs activate complex 1 of mTOR in cancer and immune cells." (PMID 37274280, 2023). "In human cancers, mTOR activation facilitates tumor cell proliferation and migration." (PMID 36809979, 2023). "The AKT/mTOR signaling pathway is one of the key mediators of cancer development." (PMID 37547758, 2023). "The local inflammatory process commonly present at the edge of cancer can explain the effect, which may have a confounding inhibitory effect on the mTOR pathway expression in this area." (PMID 37366904, 2023). "In this light, our results suggest that targeting the SMYD3 methyltransferase to disrupt the signaling balance between AMPK and mTOR in cancer cells may represent a suitable therapeutic approach." (PMID 37998381, 2023). "In this sense, using pro-senescence anti-cancer drugs, combined with mTOR inhibitors and/or autophagy inhibitors, may have preponderant effects on the SASP and, therefore, on the tissue environment." (PMID 37298236, 2023). "Furthermore, siRNA knockdowns of total PIK3CD variants, PIK3CD-L and PIK3CD-S showed differential inhibitory effects on AKT/mTOR signaling, possibly due to the differential S/L ratios in different cancer cell lines." (PMID 37670888, 2023). "Combining mTOR and immune checkpoint inhibitors, such as pembrolizumab or nivolumab, can enhance the anti-tumor immune response, which unleashes the immune system’s ability to target and destroy cancer cells." (PMID 37834408, 2023). "Hopefully, this review may promote more ideas to be generated for developing inhibitors of mTOR signaling to fight cancer and extend lifespan." (PMID 37049920, 2023). "Notably, the silencing of PVT1 reversed the multi-drug resistance in CRC, considering that mTOR is one of the primary factors in cancer drug resistance." (PMID 37280524, 2023).
cancer (continued). "The PI3K/mTOR signaling pathway is one of the most frequently dysregulated pathways in cancer, with mTOR effectively integrating metabolic information, regulating mRNA translation, and coordinating energy expenditure and mitochondrial energy production during translation." (PMID 37507746, 2023). "This means that it is possible to simultaneously delay aging and treat cancer by targeting mTOR." (PMID 37049920, 2023). "In addition to rapalogues, second-generation mTOR inhibitors have generated mTOR to combat cancer in a better way, with one class inhibiting selectively both mTORC1 and mTORC2 without having any effect on other kinases." (PMID 37513916, 2023). "The mTOR signaling pathway’s oncogenic activation contributes to the growth, proliferation, and survival of cancer cells, emphasizing the potential of mTOR pathway inhibitors to serve as efficient anti-cancer drugs." (PMID 37637052, 2023). "Numerous studies have shown that the PI3K/AKT/mTOR pathway is an essential signaling pathway that is activated by the oncogenic RET, which subsequently promotes the survival of cancer cells through the phosphorylation of mammalian target of rapamycin (mTOR) protein." (PMID 37046823, 2023). "The present study has been designed to investigate how curcumin and plumbagin work together to target the PI3K/Akt/mTOR pathway, which may have implications in cancer therapy." (PMID 37047624, 2023). "mTOR is a major signaling pathway for cancer cell growth and survival." (PMID 38156109, 2023). "The suppression of the mTOR pathway increases autophagy directly since mTOR inhibits autophagy through Ulk1 and reduces the translation of proteins, cellular growth, and proliferation, impacting cancer." (PMID 37534085, 2023). "Therefore, in clinical practice, patients diagnosed with cancer are converted from treatment based on CNIs to monotherapy with the use of a drug from the group of mTOR inhibitors." (PMID 37658979, 2023). "mTOR, a mammalian target of rapamycin, includes two complexes, mTORC1 and mTORC2, each of which demonstrates a unique function and its ability to develop cancer." (PMID 37893079, 2023). "Recent studies have revealed that KRT17 can inhibit tumor cell proliferation, migration and invasion in malignant tumors by regulating the Akt/mTOR pathway, glucose uptake, Wnt signaling pathway, epithelial-mesenchymal transition (EMT) and mTOR/S6K1 signaling pathway." (PMID 36765563, 2023). "The activation of the EGFR/PI3K/AKT/mTOR pathway has been observed in various cancer types." (PMID 37631344, 2023). "The combination of mTOR inhibitors and other anti-cancer therapies, such as NK cells, Car-T cells, PD-1 inhibitors, and PD-L1 inhibitors, could be considered." (PMID 37049920, 2023). "RNA-seq technology has allowed the discovery of new types of RNA transcripts including long non-coding RNAs (lncRNAs), which are able to regulate the gene/protein expression of many signaling pathways (e.g., the PI3K/AKT/mTOR pathway) in cancer cells by diverse molecular mechanisms." (PMID 37047267, 2023). "Several miRNAs modulate DDR in cancer cells with the involvement of mTOR and HIF1A." (PMID 36835100, 2023). "Furthermore, the latest findings on mTOR inhibitors in the treatment of various cancers are discussed." (PMID 37513916, 2023). "eIF4E-BP1, one of two major mTOR downstream effectors, regulates the expression of several proteins involved in, for example, cell cycle, angiogenesis, cell survival, cancer development, and metastasis at the translational level, thus exerting a critical effect on mTOR signaling." (PMID 37854681, 2023). "As mTOR activity is commonly dysregulated in the majority of human cancers, our work raises the plausible hypothesis that part of the beneficial effect of FASN inhibition in cancer treatment may be due to the concomitant drop in mTORC1 signalling." (PMID 37563253, 2023).
cancer (continued). "However, therapeutic interventions targeting mTOR in various cancers, notably renal and breast carcinomas, have resulted in a significant number of relapses due to the presence of feedback mechanisms in the signalling pathway." (PMID 37513916, 2023). "The EGFR/PI3K/AKT/mTOR signaling pathway is a major pathway in diverse types of cancers." (PMID 37631344, 2023). "The inhibition of the AKT/mTOR pathway was shown to induce apoptosis of cancer cells." (PMID 36765820, 2023). "The identification of mTOR signaling as a potential target for cancer therapy." (PMID 36597205, 2023). "Moreover, we reported a positive correlation between LAT1 accumulation and mTOR signal activation in clinical cancer specimens." (PMID 36768934, 2023). "By this logic, given that PC3 genes were enriched in AMPK and mTOR signaling pathways, it is possible that perturbed AMPK and mTOR signaling do not strongly underlie metabolic shifts towards increased aerobic glycolysis in highly glycolytic cancers." (PMID 36831501, 2023). "Given that both mTOR inhibitors and DNA methylation inhibitors are widely used in cancer therapy, we believe that determining the exact crosstalk between the mTOR pathway and DNA methylation can improve our ability to predict drug responses and develop better therapeutic regimens." (PMID 37088830, 2023). "Kakihara and Saeki (2014) suggested that high levels of the R2TP complex might stabilize overexpressed mTOR proteins and contribute to the malignancy of cancer." (PMID 38192347, 2023). "The AKT/mTOR pathway regulates cellular glucose metabolism, growth and reproduction, and is a recognized oncogenic driver which mediates metabolic imbalance and cell cycle progression to enhance the survival and growth of cancer cells." (PMID 37547758, 2023). "As a single agent, it exerts its anti-cancer activity through suppression of the AKT/mTOR pathway." (PMID 36835075, 2023). "Further studies may elucidate pleiotropic ANXA7 effects on cell death/proliferation that are likely to share autophagy-relevant mechanisms with the major PI3K/Akt/mTOR players detected in cancer." (PMID 37240163, 2023). "We propose that mTOR is an interesting intracellular target and its dysregulation by compound 11 may affect cancer cells growth." (PMID 37298798, 2023). "It seems that the anti-cancer effect of mTOR inibitors is dose-dependent." (PMID 37200246, 2023). "For example, the activity of major components of the phosphatidylinositol 3-kinase (PI3K)/AKT/mammalian target of rapamycin (mTOR) signaling pathway, a major signaling pathway responsible for cell proliferation and survival, are frequently deregulated in human cancers." (PMID 36984785, 2023). "The PI3K/Akt/mTOR signaling axis, defined by phosphatidylinositol-3 kinase (PI3K), protein kinase B (Akt), and mechanistic target of rapamycin (mTOR), is a complex pathway with several upstream regulators and downstream effectors that play a key role in cancer pathology." (PMID 37504935, 2023). "Such combinations may also be considered for a range of other cancer types and mTOR-opathies to not only enhance therapeutic outcome but also reduce side effects through equivalent potency at reduced drug concentration." (PMID 37202382, 2023). "The AKT/mTOR signaling pathway is a key regulator of apoptosis and autophagy in cancer cells." (PMID 38027882, 2023). "Importantly, we have highlighted the potential of mTOR signaling in aging, neurological disorders, human cancers, cancer stem cells, and drug resistance." (PMID 37779156, 2023). "Metastatic EOC in omentum may rely on FAs to fuel the high bioenergetic demand of cancer cells instead of glucose through the mTOR-dependent activation of myeloid-derived suppressor cells." (PMID 37277821, 2023). "Therefore, the PI3K/AKT/mTOR/PTEN axis is an attractive target for targeted molecular therapy including cancer." (PMID 36903626, 2023). "Dysregulation of mTOR signaling occurs in a variety of human cancers." (PMID 37372982, 2023).
cancer (continued). "In addition, there is a strong connection between Bmal1 and Per2 regulation and the PI3K/mTOR signaling pathway, one of the most frequently activated signaling pathways in tumorigenesis and the progression of cancer." (PMID 36768253, 2023). "Thus, further investigation into 5-FU anti-cancer activity combining mTOR and SESN protein interactions seems to be of great importance." (PMID 37284849, 2023). "However, oxaliplatin in adjuvant chemotherapy regimens has unexpectedly been reported to activate mTOR signaling in response to chemotherapy resistance, suggesting a biological response of cancer cells to the cell-killing mechanism of anti-cancer drugs." (PMID 36768934, 2023). "However, the signaling of mTOR is often dysregulated in different cancers, such as breast, prostate, lung, liver, and renal cell carcinomas." (PMID 36701037, 2023). "Function analysis and cMap analysis were conducted that candidate DEMs and DEGs which were screened from TCGA, GEO, GTEx and 4 databases were associated with classic cancer-related signaling pathways such as Wnt signaling pathway, TGF-beta signaling pathway and mTOR signaling pathway." (PMID 38036953, 2023). "Studies have shown that SphK1 inactivation/silencing could result in ceramide accumulation in cancer cells, which then inactivates Akt-mTOR cascade by activating phosphatases PP2A and PP1." (PMID 37604912, 2023). "Cancer immunotherapy is another promising approach for mTOR dual blockers." (PMID 38057772, 2023). "Furthermore, the in silico investigations for the identification of its probable mechanism of anti-cancer action revealed that these compounds showed good binding affinities and stable associations with the EGFR, PI3K, mTOR, and Tubulin polymerzation enzymes." (PMID 36769327, 2023). "The signaling network defined by PI3K, AKT, and mTOR proteins controls several essential biological functions such as cellular growth, cell metabolism, and survival, and as a pro-proliferative pathway is often deregulated in cancers." (PMID 37816864, 2023). "This controversial role of autophagy in modulating cellular radiosensitivity was attributed to the activation of its upstream regulatory pathways, including PI3K/Akt/mTOR, mitogen-activated protein kinases, and the unfolded protein response, in irradiation-treated cancer cells." (PMID 36890567, 2023). "According to previous studies, the role of mTOR in cancers has been well investigated." (PMID 36959615, 2023). "Similarly, mitogen-activated protein kinase (MAPK) and AKT serine-threonine kinase/mammalian target of rapamycin (Akt/mTOR) play a key role in cell proliferation in cancer cells." (PMID 37571343, 2023). "Collectively, mTOR is able to participate in intracellular and extracellular signalling, regulating multiple downstream pathways involved in a range of pathophysiological processes, such as cancer, metabolic disorders, neurodegeneration, and aging." (PMID 37489050, 2023). "Mutations in mTOR and ABL1 are noteworthy given they are activating in other cancers resulting in increased cell proliferation, and may contribute to cholangiocarcinogenesis in this fashion." (PMID 37095160, 2023). "Bufalin suppressed the levels of mTOR, p-p70S6K, and p-4EBP1 in Eca109 cancer cells." (PMID 36903477, 2023). "Furthermore, SIRT6 inhibits the IGF/AKT pathway, which is responsible for suppressing autophagy, while activating the PI3K/AKT/mTOR pathway, which promotes cancer progression." (PMID 37175631, 2023). "Cancer cells undergo a metabolic reprogramming of glycolysis, which can be mediated by mTOR." (PMID 38258072, 2023). "In addition, BCAT plays a role in supporting cancer cell growth and proliferation by promoting the biosynthesis of key molecules required for tumor development, such as activating or inhibiting the mTOR signaling pathway to affect cancer cell multiplication." (PMID 38028625, 2023).
cancer (continued). "The PI3K/AKT/mTOR pathway is one of the most frequently altered pathways in cancer." (PMID 37644594, 2023). "Additionally, the activation of the PI3K/AKT/mTOR pathway is correlated with poor prognosis in several types of cancer." (PMID 37626424, 2023). "Rapamycin, known for its ability to inhibit mTOR, has demonstrated efficacy in cancer treatment." (PMID 37759234, 2023). "Because NUAK1 inhibition synergies with Akt or mTOR blockage, we investigated the cancers where co-targeting may be used." (PMID 38135881, 2023). "With this central role in cellular homeostasis and survival, mTOR, when dysregulated, has been implicated not just in cancer, but also in metabolic syndromes, neurodegeneration, and aging." (PMID 37457922, 2023). "Furthermore, for every 1% of cells expressing mTOR in the nucleus, the odds of the cancer grade being 3 were 1054-times higher (OR = 1054.7, 95% Cl = 17.3–64354.1, p = 0.0009)." (PMID 37176048, 2023). "Thus, our study revealed a new anticancer mechanism of VC by inhibiting the mTOR pathway, thereby providing the evidence for the therapeutic potential of VC, when combined with other drugs, in cancer treatment." (PMID 36787291, 2023). "Of the twenty-two compounds with a Cmap score of 90 or greater, six have been reported to have activity in other cancer cell lines against the PI3K/Akt/mTOR pathway, five as protein synthesis inhibitors, three as protein kinase inhibitors, and three of the compounds as cell cycle inhibitors." (PMID 38132962, 2023). "For example, in cancer cells it is common that the mTOR and RAS/MAPK proteins interact." (PMID 36998738, 2023). "Thus, studies were focused to treat PTEN-inactive cancer by targeting selected components of the PI3K/AKT/mTOR signaling pathway." (PMID 37533462, 2023). "Genetic alterations or changes in upstream signaling levels can lead to abnormal activity of the mTOR signaling pathway, which may indicate tumor progression or become a new target for cancer treatment." (PMID 36994237, 2023). "Such an event indicates the probability of the existence of certain continuous conditions inside the cancer cells that makes them exhibit this mTOR kinase ligand-specific modulation, resulting in these cells being the significant therapeutic target for different mTOR inhibitors." (PMID 37602330, 2023). "The role of mTOR in cancer cell proliferation has been extensively described." (PMID 38041134, 2023). "In addition, the mTOR signaling pathway promotes cell proliferation and has been regarded as a potential anti-cancer target." (PMID 37049920, 2023). "PI3K-independent activation of mTOR has been reported in drug-resistant cancer cells." (PMID 38065968, 2023). "An imbalance in PI3K/AKT/mTOR pathway signaling in humans often leads to cancer." (PMID 37834269, 2023). "One of the most frequently activated signaling pathways in cancer is the PI3K/Akt/mTOR pathway." (PMID 37452879, 2023). "PI3K/Akt/mTOR pathway has been shown to be altered in different human cancers." (PMID 37237486, 2023). "A complex network controls apoptosis, and the PI3K/AKT/mTOR signal transduction pathway is an important pathway to regulate cell apoptosis, which regulates cell growth, survival, and migration in the process of cancer progression and metastasis." (PMID 37705007, 2023). "Therefore, targeting key molecules in the PI3K/AKT/mTOR pathway is a promising cancer treatment strategy." (PMID 37489050, 2023). "The PI3K/AKT/mTOR pathway, vital for cell growth and survival, is often dysregulated in cancers." (PMID 38067206, 2023). "Additionally, recent studies have indicated a link between m7G modifications and the mTOR pathway in the pathogenesis and progression of certain cancers." (PMID 37654606, 2023). "Akt and mTOR are therapeutic targets for cancer treatment, and A.443654 is an AKT inhibitor." (PMID 37542141, 2023).